TFPI2 (tissue factor pathway inhibitor 2)
Diseases named in the same sentence as TFPI2 in open-access papers (continued):
Sharing a sentence is not in itself a finding about the gene and the disease.
tumor (continued). "In the present study, RT-PCR analysis of total RNA from both human normal and tumor cells revealed a novel 289 nucleotide splice variant of the TFPI-2 transcript designated as aberrantly-spliced TFPI-2 (asTFPI-2)." (PMID 17352822, 2007). "The transcriptional and translational regulation of the TFPI2 gene is governed by a diverse array of molecular factors, including DNA methylation, microRNAs (miRNAs), growth factors, cytokines, and tumor-associated signaling pathways, which either promote or suppress its expression." (PMID 40361374, 2025). "Further work on HCC has demonstrated that methylation of TFPI-2 is linked to a high risk of advanced tumor stage, early tumor recurrence, poor prognosis, and that it could be a potential negative prognostic biomarker in patients with HCC after hepatectomy." (PMID 39153052, 2024). "TFPI2 has been reported to be downregulated in several types of cancer, and loss of TFPI2 function may facilitate tumor invasion and metastasis." (PMID 37238908, 2023). "SDC2 and TFPI2 methylation, which was affected by tumor location, patient age, mutation load, and microsatellite instability (MSI), may be considered methylation markers for CRC detection." (PMID 37779184, 2023). "These indicate that methylation‐associated silencing of TFPI2 plays a causal role in advanced tumor phenotypes of high‐methylation MM, which results in thicker progression, worse prognosis, and reportedly, metastasis through increasing cellular growth and invasion." (PMID 32406600, 2020). "Moreover, clarifying the mechanism underlying TFPI2 transcriptional regulation may be helpful in furthering our understanding of tumor development and progression." (PMID 29757260, 2018). "While the present study suggests a direct correlation between the production of a novel TFPI-2 transcript and tumor development, further studies are needed to determine whether the alternative splicing of TFPI-2 pre-mRNA reported here is associated with tumor progression." (PMID 17352822, 2007). "Furthermore, TFPI2 may promote M2-type tumor-associated macrophages (TAMs) via PPARγ, which support tumor growth through immune evasion, angiogenesis, and ECM remodeling by releasing factors like epidermal growth factor (EGF), hepatocyte growth factor (HGF), VEGF, MMPs, IL-10, and TGF-β." (PMID 40361374, 2025). "miRNAs suppressing TFPI2 in tumors have been reviewed, but their roles in non-tumor tissues are also significant." (PMID 40361374, 2025). "In 42 patients with localized renal cell carcinoma and 12 with metastatic renal cell carcinoma, serum TFPI2 ≥ 170 pg/mL distinguished localized renal cell carcinoma from healthy controls, with levels increasing with tumor grade." (PMID 40361374, 2025). "By regulating extracellular matrix degradation, TFPI2 contributes to extracellular matrix stabilization, inhibits pathological angiogenesis, suppresses cellular invasion, and restrains tumor growth and metastasis." (PMID 40361374, 2025). "By binding the MITF promoter, TFPI2 represses its transcription, reinforcing its tumor-suppressive function." (PMID 40361374, 2025). "TFPI2 expression inversely correlates with tumor stage and grade, with higher-grade malignancies showing reduced TFPI2 levels." (PMID 40361374, 2025). "These multilayered regulatory mechanisms explain the observed tumor-type-dependent variation in TFPI2 expression." (PMID 40765823, 2025). "While the regulation of TFPI2 in oncogenesis has been extensively reviewed in the recent literature, this section expands the discussion to include its role in non-tumor pathologies." (PMID 40361374, 2025). "The expression heterogeneity of TFPI2 across various malignancies stems from three fundamental regulatory mechanisms that collectively determine its tumor-specific expression profiles." (PMID 40765823, 2025). "In many malignancies, the TFPI2 promoter hypermethylation silences its transcription, increasing tumor aggressiveness." (PMID 40361374, 2025).
tumor (continued). "Meanwhile, emerging evidence has established TFPI2 as a positive regulator of tumor chemosensitivity across multiple cancer types." (PMID 40765823, 2025). "In other words, numerous studies have provided compelling in vitro evidence supporting the role of TFPI2 as a tumor suppressor gene." (PMID 40361374, 2025). "In vitro studies have demonstrated that TFPI2 functions as a tumor suppressor by inhibiting extracellular matrix (ECM) degradation and restraining tumor cell invasion." (PMID 40361374, 2025). "TFPI2 also regulates vascular endothelial and smooth muscle cell proliferation, key elements of the tumor microenvironment (TME)." (PMID 40361374, 2025). "Previous studies have shown that EGCG upregulates the expression of tissue factor pathway inhibitor-2 (TFPI-2), a factor negatively correlated with tumor malignancy." (PMID 40427513, 2025). "Down-regulation of TFPI-2 expression is well documented in numerous types of neoplasms, mainly via promoter methylation." (PMID 39153052, 2024). "CD24-dependent activation of Src is associated with the downregulation of tissue factor pathway inhibitor 2 (TFPI-2), a tumor suppressor gene." (PMID 38360723, 2024). "Research over the last 20 years has demonstrated that TFPI-2 protein levels are very low or undetectable in many tumor cells compared to normal cells." (PMID 39153052, 2024). "In particular, TFPI-2, a serine protease inhibitor with multi-faceted effects on tumor growth and metastasis, has attracted interest." (PMID 39153052, 2024). "It has been found and characterized that GSCs-derived TFPI2 can regulate the maintenance of tumor stem cell stemness and the migration and immunosuppression of microglia in the tumor microenvironment through different mechanisms, respectively." (PMID 39156969, 2024). "TFPI1 and TFPI2 are deemed tumour suppressors, yet their role can vary depending on the cancer type and its specific molecular environment." (PMID 39199316, 2024). "There is a growing body of evidence to suggest that TFPI-2 functions as a tumor suppressor, plays a role in regulatory mechanisms, and affects coagulation, angiogenesis, ECM degradation and expression of many other genes via epigenetic mechanisms." (PMID 39153052, 2024). "The tumor-suppressive effects mediated by AGAP2-AS1 knockdown were largely reversed following down-regulation of TFPI-2." (PMID 39153052, 2024). "TFPI-2 expression is reduced in cancer tissue, and in numerous cancer types its low-expression correlates with the advanced stage or grade of the tumor." (PMID 39153052, 2024). "Several studies have found that TFPI-2 plays a role in maintaining the stability of the tumor microenvironment and is considered a promising prognostic biomarker in several cancers." (PMID 38736872, 2024). "To investigate the effects of CYP24A1 and TFPI2 on tumor metastasis, we stably transfected BC cells and injected them into nude mice via the tail vein." (PMID 39068476, 2024). "miR-27a-3p—specific inhibitor demonstrates a significant tumor suppressor function similar to that of TFPI-2 itself." (PMID 39153052, 2024). "In BC, low levels of TFPI-2 expression correlate with tumor growth, metastasis and pathological stage." (PMID 39153052, 2024). "While TF shows tumour-enhancing characteristics, its natural inhibitors, TFPI1 and TFPI2, are associated with tumour-suppressing properties." (PMID 37569483, 2023). "In accordance with these potentially tumor-promoting properties of TF, its natural inhibitors TFPI-1 and TFPI-2 have been described to act as tumor suppressors." (PMID 36900315, 2023). "For example, the transcriptional decompression of the L1 chimeric transcript LCT13 is related to the silencing of homologous transcript TFPI-2, a tumor suppressor in various human malignancies." (PMID 37723560, 2023). "Third, in the field of cancer research, it is a well-known fact that TFPI2 can serve as a tumor suppressor gene." (PMID 37238908, 2023).
tumor (continued). "Nonetheless, in one study, the researchers successfully validated that TFPI2 is frequently methylated in a panel of primary tumor samples from OSCC." (PMID 38067304, 2023). "Based on these important findings, we conclude that MBD3 can inhibit the expression of TFPI2, indirectly relieve the inhibitory effect of TFPI2 on tumour angiogenesis, and then promote tumour metastasis." (PMID 35501390, 2022). "TFPI-2 is downregulated in aggressive cancers, such as breast cancer and glioma, and recombinant therapy or overexpression of this protein reduces tumor cell migration and invasion." (PMID 36052162, 2022). "Subcutaneous tumorigenesis experiments in BALB/c nude mice revealed that MBD3 knockdown in Huh7 cells significantly reduced tumour growth, which was partially rescued by TFPI2 co-suppression." (PMID 35501390, 2022). "TF, TFPI-1 and TFPI-2 are overexpressed by tumour cells, and experimental evidence highlights their role in VM." (PMID 36224457, 2022). "TFPI2 is a Kunitz-type serine proteinase inhibitor that has been previously identified as a tumour suppressor involved in numerous cancers." (PMID 35501390, 2022). "As a tumour suppressor, TFPI2 has been reported to be silenced through epigenetic modification and thereby contribute to tumour growth and metastasis." (PMID 35501390, 2022). "We identified that MBD3 plays a key role in promoting the proliferation, angiogenesis and invasion of HCC by inhibiting tumour suppressor TFPI2." (PMID 35501390, 2022). "Taken together, these suggest that MBD3 inhibits the expression of the tumour suppressor TFPI2, thereby undoing its inhibition of tumour angiogenesis, eventually promoting the progression and metastasis of HCC." (PMID 35501390, 2022). "TFPI-2 is instead a potent inhibitor of plasmin and MMPs that can regulate the adhesion and migration of endothelial and tumour cells in a context-dependent manner." (PMID 36224457, 2022). "To better understand the correlation between TFPI2 expression and tumour angiogenesis, we divided these samples into three groups based on TFPI2 amount, as defined by expression scores, and studied the CD34-MVD among these three groups." (PMID 35501390, 2022). "Increasing degrees of tumor malignancy is associated with the expression of TFPI-2, possibly suggesting a role for TFPI-2 in maintaining the stability of the tumor environment and inhibiting the growth of neoplasms and the formation of metastases." (PMID 33947134, 2021). "Using the same data set, univariate and multivariate Cox regression analyses were used to analyze the impact of age, sex, tumor thickness, diameter, mitotic count, stage, metastasis, and TFPI2 expression on TCGA-UM patient overall survival." (PMID 34249699, 2021). "TFPI2 showed significant correlations with tumor diameter (P = 0.027), mitotic count (P = 0.016), stage (P = 0.0045) and metastasis (P = 0.0019)." (PMID 34249699, 2021). "By inhibiting a variety of proteinases, including plasmin, trypsin, and metalloproteinases, TFPI2 can suppress tumor invasion and metastasis by regulating extracellular matrix degradation." (PMID 34249699, 2021). "Based on its strategic role in inhibition of tumor cell invasion, TFPI-2 can be considered a tumor suppressor in this type of malignant tumor." (PMID 32559232, 2020). "High‐methylation subgroup significantly correlates with more advanced tumors with greater tumor thickness and worse prognosis, and silencing of one of the most frequently methylated genes, TFPI2, is found to increase cell proliferation and invasion." (PMID 32406600, 2020). "According to genome-wide screening data, TFPI2 is assumed to be a tumor-suppressor gene inactivated by aberrant promoter methylation in different cancer types." (PMID 32559232, 2020). "For example, CD24 regulates the invasion of tumor cells by suppressing tissue factor pathway inhibitor-2 (TFPI-2) through a Src-dependent manner." (PMID 32765491, 2020).
tumor (continued). "It was high in tumor-associated fibroblasts or metastatic fibroblasts and relatively low in normal fibroblasts, and decreased in tumor cells where TFPI2 was silenced by methylation." (PMID 32559232, 2020). "In this study, we validated that TFPI2 is frequently methylated in a panel of OSCC primary tumor samples in a cancer-specific manner and that TFPI2 is transcriptionally regulated by promoter hypermethylation in OSCC cells." (PMID 31405379, 2019). "TFPI-2 has been recently recognized as a tumor suppressor, playing a suppressive role in tumor cell proliferation, apoptosis, invasion and angiogenesis." (PMID 29051606, 2017). "TFPI-2 has recently been recognized as a tumor suppressor, which not only plays a fundamental role in modulation of ECM integrity, but also involves the regulation of many oncogenes." (PMID 29051606, 2017). "In the current study, we recruited 114 GC patients, 80 CRC patients and 22 non-tumor individuals to investigate the role of TFPI2 methylation on the detection of GC and CRC." (PMID 29137404, 2017). "Our results showed that TFPI2 methylation was significantly higher in tumor tissues (GC: 29.940% vs. 12.785%, P < 0.001; CRC: 26.930% vs. 5.420%, P < 0.001)." (PMID 29137404, 2017). "The CCC-specific elevation of serum TFPI2 was consistent with the mRNA expression pattern in tumor tissues." (PMID 27798689, 2016). "Compared to CA125, obvious increases in serum TFPI2 level were observed during tumor progression in both the training and validation sets." (PMID 27798689, 2016). "Low expression of TFPI2 mRNA was found in tumor tissues of CCC patients with lower serum TFPI2 levels." (PMID 27798689, 2016). "We identified tissue factor pathway inhibitor-2 (TFPI-2), a matrix associated inhibitor of cell motility, as the functional target of trypsinogen 4, which cleaved TFPI-2 and removed it from the matrix put down by tumor-EC." (PMID 26318044, 2015). "To clarify the mechanism by which trypsinogen 4 affects the migratory capacity of tumor-EC, we investigated its relationship with TFPI-2." (PMID 26318044, 2015). "TFPI-2 has been shown to inhibit tumor angiogenesis, most likely by directly decreasing EC migration." (PMID 26318044, 2015). "The proteolytic cleavage leads to the inactivation of TFPI-2, thus blocking its ability to inhibit the migration of tumor-EC." (PMID 26318044, 2015). "Altogether these results indicated that trypsinogen 4 can reduce the extracellular availability of TFPI-2 to favor the migration of tumor-EC mediated by the tumor microenvironment." (PMID 26318044, 2015). "TFPI-2 has been described as a tumor suppressor gene that can counteract the metastatic potential of tumor cells." (PMID 26318044, 2015). "Considering its tight correlation with tumor progression, TFPI2 has thus been labeled a DNA-methylation biomarker." (PMID 26501324, 2015). "In this context, novel gene therapy tools, including recombinant adenoviral-mediated TFPI-2 delivery, are currently being developed to regulate tumor growth providing potential novel therapeutic approaches for the treatment of DLBCL in dogs." (PMID 24695110, 2014). "Based on our recent methylation array analysis involving specimens of normal oral tissues and OSCC tissues at different pathological stages, the methylation level of TFPI-2 was found to differ between normal- and tumor-tissue DNA." (PMID 25179542, 2014). "TFPI-2 expression was observed to be significantly decreased in the patients with tumor invasion or metastasis." (PMID 24396436, 2014). "The 110 oral tissue specimens analyzed by qMSP comprised 86 tumor tissues and 24 normal tissues; the TFPI-2 methylation level was significantly higher in tumors than in normal tissue (P < 0.0001)." (PMID 25179542, 2014). "Our data also showed that TFPI-2 counteracts tumor invasion by negatively regulating MMP-2 activation, consistent with the finding that TFPI-2 is associated mainly with the inhibition of ECM degradation." (PMID 25179542, 2014).
tumor (continued). "Previous studies have demonstrated that TFPI-2 suppresses tumor invasion and metastasis via its inhibitory activity on ECM degradation and remodeling." (PMID 25179542, 2014). "The observation of TFPI-2 silencing in OSCC tissues and cells inspired us to examine the tumor-suppressive role of TFPI-2 in OSCC." (PMID 25179542, 2014). "As expected from our study, TFPI2, predicted to play a tumor suppressor role in tumor development, was down-regulated when BCRP was up." (PMID 24489651, 2014). "The concept that TFPI1 imparts increased tumorigenic potential is controversial, as literature also exists suggesting TFPI1, like TFPI2, is a tumor suppressor." (PMID 24489651, 2014). "A similar pattern of TFPI-2 methylation status was obtained using pyrosequencing assay with 60 oral tissue specimens comprising 49 tumor tissues and 11 normal tissues (P < 0.0001)." (PMID 25179542, 2014). "TFPI-2 expression was detected by immunohistochemical analysis, RT-PCR and western blotting in tumor, peritumoral and gastric normal tissues from 72 patients with gastric stromal tumors." (PMID 24396436, 2014). "Tissue factor pathway inhibitor 2 (TFPI-2) is a tumor suppressor involved in invasiveness inhibition." (PMID 24695110, 2014). "Although TFPI-2 was previously shown to reduce tumor cell invasiveness, the findings regarding its influences on cell migration have been controversial." (PMID 25179542, 2014). "The results indicated that there was a significant difference in TFPI-2 expression between tumor, peritumoral and gastric normal tissues, and between tumors of different grades." (PMID 24396436, 2014). "The expression level of TFPI-2 protein was significantly increased in gastric normal and peritumoral tissues compared with that in tumor tissue, (P<0.01)." (PMID 24396436, 2014). "As shown in the target region centering on the TFPI-2 transcription start site comprising 31 CpG sites, highly dense methylation was observed in the tumor tissues, whereas the normal tissues were essentially free of methylation." (PMID 25179542, 2014). "The expression level of TFPI-2 mRNA was significantly increased in gastric normal tissue and peritumoral tissue compared with that in tumor tissue (P<0.01)." (PMID 24396436, 2014). "Consistently, ectopic expression of TFPI-2 can inhibit tumour growth and metastasis in vivo by regulating pericellular ECM remodelling and angiogenesis." (PMID 23703216, 2013). "The results suggest the patients with lower TFPI-2 expression should receive more effective systemic therapy to reduce tumor recurrence." (PMID 23497249, 2013). "Fifteen of twenty-seven patients (∼56%) displayed significant downregulation of TFPI-2 in tumours (P < 0.0001, Wilcoxon matched-pairs signed rank test)." (PMID 23703216, 2013). "TFPI-2 inhibits the activity of plasmin and a variety of matrix metalloproteinases (MMPs), which are important to tumor invasion and metastasis." (PMID 23497249, 2013). "The AI clearly increased together with tumor progression in the TFPI-2 positive samples, this being statistically significant." (PMID 22208663, 2012). "Clearly, the immunostaining of TFPI-2 decreased together with tumor progression, this being statistically significant (p < 0.005)." (PMID 22208663, 2012). "Recent findings suggest decreasing TFPI-2 expression plays a significant role in inhibiting cell migration and tumor invasion by a mechanism that involves its inhibitory activity." (PMID 22208663, 2012). "Recently, down regulation of TFPI-2 was suggested to be involved in tumor invasion and metastasis in some cancers." (PMID 22208663, 2012). "The mechanism of downregulation of TFPI-2 expression during tumor progression was significantly correlated with the promoter aberrant methylation." (PMID 22208663, 2012). "In conclusion, our data shows the expression of TFPI-2 in cervical lesions has a decreasing trend with tumor progression." (PMID 22208663, 2012).